RN7SKP27 (RN7SK pseudogene 27)
Gene: Miscellaneous RNA gene on chromosome 2 (22,861,552 to 22,861,884, forward strand). Ensembl gene ENSG00000222616.
Homologues: Orthologues: chimpanzee 7SK (99% identical), mouse Gm54885 (55% identical), guinea pig 7SK (53% identical), mouse Gm55949 (47% identical), mouse Gm54941 (16% identical). Paralogues in human: RN7SKP79 (64% identical), 7SK (63% identical), RN7SKP173 (63% identical), RN7SKP180 (63% identical), RN7SKP170 (62% identical), RN7SKP230 (62% identical), RN7SKP124 (62% identical), RN7SKP48 (62% identical), RN7SKP184 (62% identical), RN7SKP189 (62% identical), RN7SKP211 (62% identical), RN7SKP217 (62% identical), and 284 more.